INTS10 (integrator complex subunit 10)
Description:
Component of the integrator complex, a multiprotein complex that terminates RNA polymerase II (Pol II) transcription in the promoter-proximal region of genes. The integrator complex provides a quality checkpoint during transcription elongation by driving premature transcription termination of transcripts that are unfavorably configured for transcriptional elongation: the complex terminates transcription by (1) catalyzing dephosphorylation of the C-terminal domain (CTD) of Pol II subunit POLR2A/RPB1 and SUPT5H/SPT5, (2) degrading the exiting nascent RNA transcript via endonuclease activity and (3) promoting the release of Pol II from bound DNA. The integrator complex is also involved in terminating the synthesis of non-coding Pol II transcripts, such as enhancer RNAs (eRNAs), small nuclear RNAs (snRNAs), telomerase RNAs and long non-coding RNAs (lncRNAs). Within the integrator complex, INTS10 is part of the integrator tail module that acts as a platform for the recruitment of transcription factors at promoters. May be not involved in the recruitment of cytoplasmic dynein to the nuclear envelope, probably as component of the integrator complex.
Synonyms: Int10; C8orf35; FLJ10569
Tractability: PROTAC: UniProt records ubiquitination sites on it; ubiquitination databases record sites on it; its protein half-life has been measured.
Gene: Protein-coding gene on chromosome 8 (19,817,339 to 19,853,282, forward strand). Ensembl gene ENSG00000104613.
Subcellular location: Nucleus
Subcellular location (Human Protein Atlas): Cytosol; Nucleoplasm
Pathways (Reactome):
Gene expression (Transcription): RNA polymerase II transcribes snRNA genes
Gene Ontology:
Molecular function: protein binding
Biological process: regulation of transcription elongation by RNA polymerase II; RNA polymerase II transcription initiation surveillance; snRNA processing
Cellular component: INTAC complex; integrator complex; nucleus; nucleoplasm
Genetic constraint (gnomAD): Loss-of-function variants: 27 observed, 54.3 expected, observed/expected ratio (o/e) 0.5, 90% interval 0.37 to 0.69. The upper end of that interval is the gene's LOEUF score, 0.69, which puts it in group 2 of 6, group 1 being the genes least tolerant of losing a copy. Missense variants: 524 observed, 591.23 expected, observed/expected ratio (o/e) 0.89, 90% interval 0.82 to 0.95. Synonymous variants: 229 observed, 227.57 expected, observed/expected ratio (o/e) 1.01, 90% interval 0.9 to 1.12.
Homologues: Orthologues: chimpanzee INTS10 (99% identical), macaque INTS10 (99% identical), dog INTS10 (98% identical), guinea pig INTS10 (97% identical), rabbit INTS10 (97% identical), rat Ints10 (96% identical), mouse Ints10 (96% identical), tropical clawed frog ints10 (82% identical), zebrafish ints10 (68% identical), Drosophila melanogaster IntS10 (22% identical).
Diseases named in the same sentence as INTS10 in open-access papers:
INTS10 is named in the same sentence as 10 diseases in open-access papers, as found by Europe PMC text mining. Sharing a sentence is not in itself a finding about the gene and the disease. The quoted sentences say what the papers report.
chronic hepatitis B (1 paper, 2025). "Previous work has shown that both INTS10 and IRF3 expression are reduced in patients with chronic hepatitis B compared to individuals who have achieved spontaneous viral resolution." (PMID 41383743, 2025). "In particular, a negative relationship was identified between INTS10, HBeAg, HBsAg, HBV DNA, and TBA in patients with HBeAg-positive chronic hepatitis B, but not in those who were HBeAg-negative." (PMID 41383743, 2025). "Nevertheless, the relationships among INTS10 expression, IRF3, and HBV replication in patients with chronic hepatitis B (CHB) have not been comprehensively examined." (PMID 41383743, 2025).
enterovirus infections (1 paper, 2026). "Similarly to that observed in CVB3-infected cells, a cleavage fragment of INTS10 appeared in both EV-A71- and CAV16-infected cells (red arrows), indicating that INTS10 cleavage is a shared feature of enterovirus infections." (PMID 41596640, 2026).
hepatoma (1 paper, 2016). "INTS10 can also efficiently reduce the HBV markers in human hepatoma cell line HepG2.2.15 which constitutively produces HBV, and in human hepatoma cell line HepG2 which was co-transfected with the pAAV-HBV1.2 vectors." (PMID 27244555, 2016).
virus infection (1 paper, 2026). "The cleavage of INTS10 leads to disrupted host transcription and innate immune responses, which in turn promote virus infection." (PMID 41596640, 2026). "The limitation of this study is that we did not explore the role of cleaved INTS10 fragments in virus infection." (PMID 41596640, 2026).
cancer (5 papers, 2016 to 2025). A tumor composed of atypical neoplastic, often pleomorphic cells that invade other tissues. "In particular, C7orf26 shows similar dependency landscape to INTS10/13/14, but not genes encoding other integrator complex subunits, across 1086 pan-cancer cell lines." (PMID 37460547, 2023). "INTS10 is part of the integrator complex, a complex of proteins that is mainly involved in the transcription of small nuclear RNAs, but has also been linked to transcriptional pausing and has not been linked to cancer previously." (PMID 28027311, 2016). "We also detected an interaction between the Drosophila C7orf26 ortholog and fly Integrator and observed co-essentiality between C7orf26 and INTS10, INTS13, and INTS14 in the Cancer Dependency Map (Data S2)." (PMID 35688146, 2022).
infection (1 paper, 2026). The state of being infected such as from the introduction of a foreign agent such as serum, vaccine, antigenic substance or organism. "We propose that the targeted cleavage of INTS10 by CVB3 3Cpro serves to disrupt the cellular antiviral responses triggered during infection." (PMID 41596640, 2026). "We observed that the quality of full-length INTS10 reduced, and a small fragment with a molecular weight (MW) less than 55 kDa emerged at 9 h post-infection (red arrows)." (PMID 41596640, 2026).
INTS10 also shares sentences with these, for which no sentence is quoted: Anxiety (2 papers); Apathy (1); bladder cancer (1); hepatitis B (1).